NLRP3 (NLR family pyrin domain containing 3)
Diseases named in the same sentence as NLRP3 in open-access papers (continued):
Sharing a sentence is not in itself a finding about the gene and the disease.
tumor (continued). "We performed mIHC assays to study the associations between M1/M2 macrophage numbers and p-NF-κB p65 and NLRP3 levels in the tumor tissues of NSCLC patients who received immunotherapy." (PMID 38062129, 2024). "They found that in TAMs treated with carboplatin, there was evidence of increased NLRP3 inflammasome activation demonstrating a phenotypic change to promote anti-tumour activity." (PMID 39516433, 2024). "In this review, we discuss the possible role of NLRP3 inflammasome in the mediation of tumor growth and spread and its potential therapeutic use." (PMID 39769450, 2024). "On the other hand, no statistically significant but slightly decreased profile of both caspase-1 and IL-1β in contact with PTX before and after NLRP3 knock-down demonstrated the ability of PTX to stimulate tumor cell death." (PMID 39433537, 2024). "The cytokine release mediated by the NLRP3 inflammasome in various cell types contributes to the formation of an inflammatory tumor microenvironment through autocrine and paracrine signaling mechanisms." (PMID 39351349, 2024). "In colon cancer, activation of NLRP3 functions as a tumor suppressor by mediating the production of IL-18, which reinforces the killing activity of natural killer cells against metastatic tumor cells or down-regulates IL-22BP to suppress tumorigenesis." (PMID 39351349, 2024). "To confirm the role of NLRP3 on the effects of cryptotanshinone in 5,637 cells, we first pretreated tumor cells with LPS, then transfected them with an NLRP3-overexpression plasmid (pcDNA3.1-NLRP3) and afterward treated them with 4 μM cryptotanshinone." (PMID 39144184, 2024). "Caspases and inflammasomes play critical roles in regulating apoptosis and the inflammatory response in tumor cells, including caspase-3 and NLRP3 inflammasome." (PMID 39275245, 2024). "NLRP3 activation therefore represents a key immune checkpoint within the tumor microenvironnement, acting as a master switch for inflammation-mediated tumor progression." (PMID 39882243, 2024). "It has been demonstrated that Toll-like Receptor4 (TLR4) can participate in signaling, such as NF-B and NLRP3, to facilitate tumor metastasis." (PMID 39494337, 2024). "The increasing scientific interest in the mechanisms interconnecting inflammation and tumorigenesis has led to the study of the NLRP3 inflammasome in the setting of various neoplasms." (PMID 38397043, 2024). "Inflammatory vesicles, with the NLRP3 inflammatory vesicle being the most extensively studied among them, can affect both the occurrence of tumor cells and the composition of the tumor microenvironment." (PMID 38001342, 2024). "In vivo study, we discovered that melatonin can suppress tumor angiogenesis and lymphangiogenesis, as well as tumor growth, by downregulating the expression of the NLRP3 pathway." (PMID 39230586, 2024). "It has also been suggested that the NLRP3 inflammasome can activate the tumor suppressor STAT1 in the colon through IL-18-mediated interferon gamma (IFN-ɣ) production." (PMID 38182564, 2024). "To further elucidate the role of NLRP3 re‐expression in promoting pyroptosis in CRC in vivo, we utilised a subcutaneous xenograft tumour model by implanting NLRP3‐overexpressing SW620 cells." (PMID 38804602, 2024). "We further detected the expression of ferroptosis‐associated proteins (HMGCR, GPX4) and pyroptosis‐associated proteins (such as NLRP3, GSDMD) in tumor tissues by using immunohistochemistry or western blot." (PMID 38178583, 2024). "NLRP3 inflammasome acts as a negative regulator of tumorigenesis in HNSCC, and blocking NLRP3 inflammasome can also delay the tumor-bearing speed in HNSCC mice." (PMID 39403369, 2024). "Tumor etiology involves dysregulated activation of the NLRP3 inflammasome, although its significance in the initiation and development of cancers is still controversial given the contradictory results thus far." (PMID 38904007, 2024).
tumor (continued). "First, activation of TAMs releases IL‐1α and IL‐1β to act on tumour cells, activating the intracellular NF‐κB pathway, which next exerts a pro‐coagulant effect by affecting NLRP3 inflammatory vesicles." (PMID 38652105, 2024). "In this review, we discuss the mechanism and role of NLRP3 in tumors of the digestive system and response strategies to modulate NLRP3 for potential use in tumor treatment." (PMID 38182564, 2024). "It was found that activation of NLRP3 in tumors helped to initiate immune responses against tumor cells, which is thought to be a possible effective mechanism for sustained anti-tumor immunity." (PMID 38553639, 2024). "The resultant release of DAMPs such as ATP can lead to NLRP3 inflammasome activation and promote downstream anti-tumour activity in both murine and human OC cells in vitro." (PMID 39516433, 2024). "For instance, NLRP3 deficiency in methylcholanthrene (MCA)-induced fibrosarcoma models delayed tumor onset and improved tumor-free survival." (PMID 39301197, 2024). "Crucially, several anticancer agents can prompt pyroptosis in tumour cells by stimulating the NLRP3 inflammasome and the subsequent GSDMD pathway." (PMID 38804602, 2024). "Through the transfer of exosomal miR‐1246, tumor cells reprogram macrophages into a tumor‐supporting type (M2‐like TAMs), partially via repressing NLRP3 expression." (PMID 38342611, 2024). "Over a 12‐day period, NLRP3‐overexpressing tumours displayed attenuated tumour growth and reduced final tumour burden in response to regorafenib or 5‐FU treatment, compared to control xenografts." (PMID 38804602, 2024). "Considering that NLRP3 can exert its tumor-promoting effects in DLBCL via its effector cytokine IL-18, we should comment on several studies investigating the prognostic significance of IL-18 expression in this setting." (PMID 38397043, 2024). "On the other hand, NLRP3 inflammasome activation can lead to excessive production of inflammatory cytokines such as IL-1β and IL-18, significantly affecting the tumor microenvironment and potentially promoting HCC growth." (PMID 39544286, 2024). "NLRP3 inflammasome activation, such as IL-1β and IL-18 production, promotes immune cell infiltration in the tumor microenvironment and enhances chemotherapy-induced anti-tumor immunity." (PMID 38575922, 2024). "Elevated IL-1β levels, coupled with the hyperactivation of the NLRP3 inflammasome, are frequently observed in hematologic malignancies, and exhibit a strong correlation with tumor progression and unfavorable prognosis." (PMID 38730609, 2024). "Caspase-1, IL-1β, and IL-18 are down-regulated in NSCLC tumor tissues, and simvastatin activates NLRP3-caspase-1-IL-1β and IL-18 pathways to induce pyroptosis and inhibit NSCLC cell migration." (PMID 38654314, 2024). "Proinflammatory factors can reduce GPX4 levels and trigger ferroptosis in tumor cells, and NLRP3 knockdown in mice can improve the levels of GPX4 in the brain." (PMID 37752806, 2024). "High levels of NLRP3 have been detected in CRC tumor tissues with advanced tumor, node, and metastasis (TNM) stages, which are characterized by distant metastasis, vascular invasion, and positive lymph nodes." (PMID 38543085, 2024). "We revealed that the NLRP3 inflammasomal axis strongly enhanced tumor-related angiogenesis and lymphangiogenesis in the A549/THP-1 co-culture system." (PMID 39230586, 2024). "PTX-treated tumor cells transfected with NLRP3 siRNA were unable to up-regulate NLRP3 and ASC expression." (PMID 39433537, 2024). "Cucurbitacin B directly binds to TLR4 to activate NLRP3 inflammasome and pyroptosis, thereby playing an anti-tumor role inNSCLC." (PMID 38654314, 2024). "Targeting cell death related-molecules such as Bcl-2 family proteins and NLRP3 effectively represses tumor growth." (PMID 38575922, 2024).
tumor (continued). "Next, these cells were incubated with a low or high dose of cryptotanshinone to assess its effects on tumor cell malignant behaviors as well as transfected with NLRP3 cDNA to confirm the role of NLRP3 in BC cells in vitro." (PMID 39144184, 2024). "Several investigations reported that NLRP3 expression in TAMs was strongly correlated with tumor progression and metastasis." (PMID 39230586, 2024). "Four potential antigens associated with tumor pyroptosis (CARD8, NAIP, NLRP1, and NLRP3) were screened as candidate molecules for future mRNA vaccine development." (PMID 38166691, 2024). "Four tumor pyroptosis-associated antigens, CARD8, NAIP, NLRP1, and NLRP3, were screened as potential candidates for LUAD mRNA vaccine development." (PMID 38166691, 2024). "Tumor cell-intrinsic mechanisms of NLRP3 activation in the tumor microenvironment has been described by Tengesdal." (PMID 39882243, 2024). "Instigating pyroptosis can lead to atypical inflammasome activation, especially involving the NLRP3 inflammasome, which exerts a promotive effect on tumor inception and metastasis." (PMID 38001342, 2024). "We ablated GSDMD in the whole body and in hematopoietic cells in these CRC models, and now report a tumor-promoting role of GSDMD in sporadic CRC that is dependent on NLRP3 and gut bacteria." (PMID 38898209, 2024). "The conducted study illustrated the effects of pharmacological or genetic regulation of NLRP3 inflammasome in order to facilitate the anti-tumor effects of PTX for TNBC eradication." (PMID 39433537, 2024). "Similar protective effects are observed in breast cancer and melanoma models, where NLRP3 knockout decreased tumor growth, reduced metastasis, and enhanced survival." (PMID 39301197, 2024). "Despite the limited empirical support, emerging evidence suggests a potential tumor suppressor role for NLRP3 in CLL." (PMID 38730609, 2024). "An activating product of C3b forms a complex with PPIL1 (Peptidylprolyl Isomerase Like 1), which induces NLRP3 inflammasome formation, as evidenced by caspase-1-dependent IL-1β activation, to promote tumor metastasis." (PMID 38894892, 2024). "Studies have shown that high NLRP3 expression advances CRC tumor characteristics and supports the microenvironment, facilitating metastasis." (PMID 38543085, 2024). "ATP from the pyroptosing tumor cells subsequently activates the NLRP3 inflammasome in macrophages, resulting in caspase-1 activation and downstream GSDMD and IL-1β processing and release." (PMID 38391959, 2024). "NLRP3‐high expressing tumour cells showed significantly higher LDH release than NLRP3‐low expressing cells, suggesting that high levels of NLRP3 lead to increased cell membrane damage." (PMID 38804602, 2024). "Melatonin treatment and NLRP3 knockdown significantly inhibit tumor growth and downregulate NLRP3 and IL-1β expression in tumor tissues." (PMID 39230586, 2024). "In this setting, the implication of the NLRP3 inflammasome in carcinogenesis has gained increasing scientific attention, whereas its activation acts both as a tumor-promoting and a tumor-protective factor." (PMID 38397043, 2024). "Hydrogen is also likely to alleviate tumor volume and weight in the xenograft mouse model through the ROS/NLRP3/caspase-1/GSDMD-mediated pyroptotic pathway." (PMID 39011036, 2024). "Chronic arsenic exposure induced changes in bladder epithelial cells, which gave them tumor cell characteristics and increased the expression of NLRP3 inflammation-related factors, ROS and NOX2." (PMID 39201564, 2024). "In breast cancer, cancer-associated fibroblasts (CAF), another abundant cell type in the TME, facilitate tumor growth and metastasis through inflammasome signaling, a process attenuated when NLRP3 or IL-1β is specifically ablated." (PMID 38540172, 2024). "In a carcinogen-induced OSCC model, the intracellular ROS induced by 5-FU enhanced the NLRP3 inflammasome and IL-1β expression, which in turn mediated the onset of chemoresistance and tumor cell proliferation." (PMID 38904007, 2024).
tumor (continued). "In present study, compared with tumor model group, the expression of NLRP3, caspase 1, GSDMD and the level of IL-1β and IL-18 in XRZYBXD high dose group were increased." (PMID 40046008, 2024). "Emerging evidence has revealed that various anticancer therapies can elicit GSDMD‐dependent tumour cell pyroptosis by activating the NLRP3 inflammasome, including chemotherapy and targeted therapy." (PMID 38804602, 2024). "In particular, special interest has been given to understand the NOD-like receptor family (NLR), pyrin domain containing 3 (NLRP3) inflammasome activation mechanism and its consequences on tumor initiation, progression and metastasis." (PMID 39433537, 2024). "For instance, TMEM176B has been shown to inhibit the activation of the NLRP3 inflammasome, linking adaptive and innate anti-tumor responses." (PMID 39170226, 2024). "On the other hand, NLRP3 activation can also be harmful, as chronic inflammation driven by NLRP3 supports tumor progression by creating an environment that facilitates cancer cell proliferation, migration, invasion, and metastasis." (PMID 39769450, 2024). "Studies have shown that in tumor cells undergoing Snail-mediated epithelial-mesenchymal transition (EMT), the activity of NLRP3 inflammasomes in tumor-associated macrophages (TAMs) is diminished in response to chemotherapeutic agents." (PMID 39300122, 2024). "It was further noted that genes including capase-8, MLKL, FADD, and TRADD were upregulated in the tumor samples, while caspase-7, NLRP3, RIPK1, and RIRP3 were downregulated in expression." (PMID 38553639, 2024). "This interaction underscores the potential role of BA in modulating NLRP3-caspase-1 signaling, thereby facilitating the release of inflammatory factors during tumor cell pyroptosis via the NF-κB pathway." (PMID 38169542, 2024). "In the second part of this study, we proposed a possible anti-tumor strategy that involved NLRP3 inflammasome modulation using both pharmacological and molecular inhibitors followed by the classical administration of the anti-tumor agent PTX." (PMID 39433537, 2024). "In brief, high rates of strong NLRP3 expression occurred in patients with a tumor diameter >2 cm, MIBC, and tumor metastasis." (PMID 39144184, 2024). "Aberrant activation of NLRP3 within the tumor microenvironment results in increased IL-1β and IL-18 secretion." (PMID 39882243, 2024). "Adding to the accumulating data on solid tumors, a recently increasing number of studies investigate the role of the NLRP3 inflammasome in the pathogenesis of hematologic malignancies, with most of them focusing on neoplasms of myeloid origin." (PMID 38397043, 2024). "Their results revealed that the NLRP3 inflammasome exerted a tumour-promoting effect by activating caspase-1 in PCa." (PMID 38103146, 2024). "The NF-κB/NLRP3 signaling pathway can regulate TAM polarization to improve the tumor’s inflammatory microenvironment." (PMID 39201564, 2024). "In the presence of high levels of ROS, elevated TXNIP protein activates NLRP3 inflammasome and activates a range of downstream genes, leading to chronic inflammatory and promoting tumor occurrence and progression 15,16." (PMID 38903927, 2024). "Regarding DLBCL, NLRP3 inflammasome activation was shown to promote tumor growth and drug resistance." (PMID 38397043, 2024). "Our findings indicate that both MLT group and si-NLRP3 group significantly suppressed the mRNA and protein expression levels of NLRP3 and downstream IL-1β in tumor tissues." (PMID 39230586, 2024). "Next, we incubated 5,637 cells with 100 μg/mL LPS for 12 hr in vitro to mimic the inflammatory tumor microenvironment and assessed NLRP3 expression." (PMID 39144184, 2024). "The role of the NLRP3 inflammasome therefore appears to be secondary in this inflammatory tumor microenvironment, after Transforming growth factor β (TGF-β)." (PMID 39882243, 2024).
tumor (continued). "In the xenograft tumour model, NLRP3‐overexpressing tumours were significantly smaller than wild‐type tumours under combined treatment with 5‐FU and oxaliplatin." (PMID 38804602, 2024). "For instance, MEG3 is a tumor suppressor in many cancers, while NLRP3 regulates inflammation and cell death, which play crucial roles in tumorigenesis." (PMID 37511974, 2023). "There is increasing evidence that NLRP3-related pyroptosis is crucial for the progression of cancer, as well as tumour drug resistance." (PMID 37156816, 2023). "For example, NLRP3 inflammasomes in DCs are activated allowing for IL-1β secretion when ATP from dying tumor cells acts on P2 purinergic receptors (P2X7) purinergic receptors from DCs." (PMID 36932407, 2023). "TLR2, TLR4, and inflammasome inducing MR, NLRP3 can lead to tumor progression via the production of inflammatory cytokines (IL6, IL16), increased cell proliferation, and resistance to apoptosis (TNFAIP3)." (PMID 37599366, 2023). "Next, we sought to identify the tumor‐derived factors that engaged in direct activation of the NLRP3 inflammasome in the co‐cultured DCs." (PMID 37786300, 2023). "Apart from acting as a priming agent in human normal prostate cells, benign BPH-1, and tumor PC-3 cell lines, hypoxia also resulted in enhanced activation of NLRP3 inflammasome." (PMID 37819510, 2023). "Depending on the molecular classification of BC, the RNA transcript level of NLRP3 was higher in TNBC cells compared to luminal A group in BC cells derived from the primary tumor site and metastatic site." (PMID 36902278, 2023). "On the contrary, a substantial body of evidence attests to the critical role that NLRP3 plays in restraining tumor growth and spread." (PMID 37289257, 2023). "Earlier study has already demonstrated that granzyme A can cleave and activate GSDMB, a member of gasdermin protein family in a NLRP3‐dependent manner, then induce tumor cell pyroptosis and mediate tumor immunotherapy." (PMID 37817895, 2023). "While the effect of NLRP3 activation on tumor development is controversial, the inflammasome-dependent activation of caspase-1 is reported to have an antitumor effect." (PMID 37308559, 2023). "At the molecular level, we used IHC assays for the mouse tumor tissues to test the expression status of NLRP3 and cleaved caspase-1 (pyroptosis related proteins), and found that the combined treatment induced a higher degree of pyroptosis than monotherapy." (PMID 37705753, 2023). "NLRP3 is the most widely studied inflammasome that not only regulates the tumor itself, but also influences the composition of the tumor microenvironment." (PMID 37497237, 2023). "The targeting of miRNAs in combination with anti-tumor drugs has gained wider attention over the past few years because it improves the survival rate of cancer patients by activating NLRP3 in oncogenic pathways." (PMID 37300757, 2023). "ROS induction resulted in NLRP3 inflammasome activation and cellular autophagy, upregulating tumor vascularization." (PMID 37107298, 2023). "PMA-induced NETs have been shown to upregulate NLRP3 and IL-1β levels via a NF-κB signaling pathway in the tumour microenvironment in vitro." (PMID 36743304, 2023). "The release of IL-18 mediated by the NLRP3 inflammasome increases the expression level of effector T cells, enhancing the effect of anti-tumor immunity." (PMID 37705746, 2023). "Bioinformatic analysis of human tumor samples showed that UM has significantly lower expression of NLRP3 and IL‐1β compared with CM." (PMID 36707938, 2023). "In the liver metastatic colon cancer model, IL-18 is required for the suppression of Nlrp3 inflammasome on tumor growth and its promotion of intratumoral NK cell maturation and tumoricidal activity." (PMID 36973277, 2023). "The reduction in tumor growth by the combination of dexamethasone plus NLRP3 blockade resulted in the optimal prevention of T cell exhaustion." (PMID 36672229, 2023).